IL1B (interleukin 1 beta)
Diseases named in the same sentence as IL1B in open-access papers (continued):
Sharing a sentence is not in itself a finding about the gene and the disease.
breast cancer (continued). "Furthermore, the proinflammatory factors IL-1β, IL-8, and TNF-α, were highly expressed in breast cancer cells and tissues, and they were inhibited in MCF-7 breast cancer cells by downregulating the expression of ORM1." (PMID 35188865, 2022). "Therefore, it is of great importance to study the relationship between inflammatory factors (IL-1β, IL-8, TNF-α) and breast cancer." (PMID 35188865, 2022). "Therefore, this meta-analysis will focus on the effects of exercise on IL-6, IL-10, IL-1β, CRP, TNF-α, IGF-1 and IGFBP-3 levels in breast cancer patients." (PMID 36482346, 2022). "Specifically, IL-1β induces SNAIL and suppresses E-cadherin expression in gastric cancer cells and IL-18 downregulates claudins, which are also tight junction proteins, thereby enhancing breast cancer cell migration." (PMID 36293159, 2022). "For this reason, in a female mammary tumor model, we studied whether BPA treatment could affect the intratumoral expression of IL-1β, IL-4, IL-6, IL-10, TNF-α, IFN-γ, and VEGF by confocal microscopy immunofluorescence." (PMID 35269666, 2022). "In addition to TGF-β1, IL-1β has been demonstrated to induce EMT in normal kidney (HK-2 cells), stomach cancer (SNU719), and breast cancer (MCF-7)." (PMID 35684095, 2022). "Importantly, inhibition of IL-1 signalling with the anti-IL1β antibody Canakinumab, or the IL1R antagonist, Anakinra, inhibits bone metastasis in pre-clinical models of breast cancer." (PMID 36230739, 2022). "It is known that non-metastatic breast cancer cells do not express IL-6 and IL-8; our data showed that treatment with IL-1β induced their expressions, through the de-methylation of their promotors." (PMID 36499741, 2022). "On the other hand, this secretome could be beneficial, as IL-1β was shown to inhibit melanoma growth in vivo, and IL-6, as well as IL-8, could not only induce but also reinforce senescence in the MCF-7 breast cancer cell line." (PMID 35563820, 2022). "The possible roles of pyroptosis-related inflammasomes, gasdermins, and cytokines like interleukin-1β (IL-1β) and interleukin-18 (IL-18) in the TME of breast cancer are further elucidated to explore potential targets contributing to fight against breast cancer." (PMID 36119049, 2022). "It was highlighted how the induction of tumor progression and bone metastasis by Interleukin-1 beta, in a non-metastatic breast cancer cell line, MCF-7, was dependent on the de-methylating actions of ten-eleven translocation proteins (TETs)." (PMID 36499741, 2022). "We found that 5 ng/mL mouse recombinant IL1β did not promote the migration of breast cancer cells, while genetic overexpression of IL1β increased the migration of E0771 (p = 0.003) and Py8119 cells (p = 0.0776)." (PMID 36230739, 2022). "Xiao and colleagues found that the CTSC could promote lung metastasis of breast cancer through mediating recruitment of neutrophils and formation of neutrophil extracellular traps based on the CTSC/PR3/IL-1β axis." (PMID 36276992, 2022). "In addition to IL-6, TGF-b1 and IL-1b have been found to enhance the expression and secretion levels of OPG in mouse stromal cells and breast cancer cell lines, respectively." (PMID 36359766, 2022). "In addition, elevated serum concentrations of IL-6, IL-10, IL-1β, and TNF-α are found in a variety of cancer types, including breast cancer." (PMID 36482346, 2022). "In breast cancer, the NLRP3 inflammasome and IL‐1β production induce the infiltration of myeloid cells, such as tumor‐associated macrophages (TAMs) and myeloid‐derived suppressor cells, forming an inflammatory microenvironment and thus promoting breast cancer progression." (PMID 36176733, 2022). "Another study has confirmed that pyroptosis induced by NLRP3 and IL-1β secretion might adjust the TME towards an immune suppressive milieu, which facilitates cancer proliferation and invasion in mouse and human breast cancer." (PMID 36119049, 2022).
breast cancer (continued). "Our research revealed also that not-treated with ME breast cancer cells display an increased mRNA expression of IL-1β and IL-6 in response to heat at 39 °C alone but not to 41 °C." (PMID 34201348, 2021). "This also means that proteins like caspase-1, IL-1β and GSDMD may affect the development and prognosis of breast cancer, providing new molecular targets for the clinically targeted treatment of breast cancer." (PMID 34381721, 2021). "Interestingly, IL-1β reportedly maintains metastatic breast cancer cells along the ZEB1-positive differentiation route, which indicates that IL-1β is capable of inhibiting MET and colonization." (PMID 34522213, 2021). "Similarly, another mouse model of breast cancer showed that the therapeutic effect of doxorubicin depended on IFN-γ production by CD8+ T cells and that IL-17 and IL-1β induction was required to achieve a therapeutic effect." (PMID 34638242, 2021). "In our previous research, we found that pre-activating hUCMSCs with IL-1β could induce membrane-bound TRAIL expression and enhance apoptosis of MDA-MB-231, MCF-7 and MDA-MB-453 breast cancer cell lines (unpublished data)." (PMID 34282169, 2021). "Moreover, in breast cancer patients, PTEN expression is correlated with IL-1β expression and to anthracyclines-based adjuvant chemotherapy sensitivity." (PMID 32635472, 2020). "Additionally, E2 and G-1 induced IL-1β expression in CAFs, while in MCF-7 and SKBR3 breast cancer cell lines they promoted IL1R1 expression, stimulating migration and invasion of breast cancer cells." (PMID 32973677, 2020). "Anti-IL-1β antibodies, just like anti-IL-6, attenuated EMT phenotype in breast cancer cells." (PMID 32635472, 2020). "Moreover, ICAM3, CCL16, PDE3A, PRTN3, TRAF6, BCAR1, IL-1α, IL-1β, NFκB1, SOX2 and OCT4 decreases the protein expression as indicated by immunofluorescence staining in the ibuprofen-treated MDA-MB-231 breast cancer cells versus the control." (PMID 32528119, 2020). "In accordance, IL-1β-blockade synergizes with anti-PD-1 immune checkpoint blockade in 4T1 breast cancers by restoring the cytotoxic capacity of CTLs without inducing systemic inflammation." (PMID 32733461, 2020). "Similarly, murine 4T1 breast cancer cells release soluble CD44, which in turn induces macrophage-mediated IL-1β production, leading to tumor growth and lung metastases." (PMID 32635472, 2020). "Finally, we confirmed that P2Y2R activation by ATP mediated IL-1β and VEGF-A production and subsequent invasiveness of breast cancer cells through activation of NLRC4, ASC, and caspase-1 of inflammasome components." (PMID 32397236, 2020). "Examples of diseases that can reliably be diagnosed through salivary analysis are pancreatic (miR-3679-5p and miR-940), lung (cytokines IL1RN, IL1B, CXCL10), and breast cancers (phenylalanine, tryptophan), as well as myocardial infarction (C-reactive protein, myoglobin, and myeloperoxidase)." (PMID 32019170, 2020). "Our findings demonstrated that chronic exposure to pesticides impairs the systemic cytokine production in breast cancer patients, which leads to lower levels of both TNF-α and IL-1β under specific clinicopathological conditions, when compared to the unexposed group." (PMID 32984049, 2020). "In contrast, the IL-1β/IL-1R1/β-catenin signaling pathway that regulates c-MYC, cyclin D1 (CCDN1), SNAIL1, and matrix metallopeptidases (MMP) 2 expression promotes proliferation, migration, and invasion in breast cancer." (PMID 32397236, 2020). "Previous work by our group has shown that binding of the inflammatory cytokine IL-1β to its receptor IL-1RI, present in non-invasive MCF-7 breast cancer cells, triggered the initiation of epithelial–mesenchymal transition (EMT) by activation of the signaling pathway IL-1β/IL-1R/β-catenin." (PMID 32244518, 2020).
breast cancer (continued). "MCM and hCM greatly increased the expression of IL-6, IL-1β, IL-1α, TNF-α, IGF-1, and MCP-1 compared with control at the mRNA levels in MCF-7 and MDA-MB-231 cells, while the little effect on the VEGF expression in mCM treated-breast cancer cells." (PMID 32201525, 2020). "Furthermore, adipocyte- or CAA-secreted factors, including leptin, TNF-α, IL-6, IL-1β, IGFBP-2, LCN2, collagen VI, and others, have also been demonstrated to promote breast cancer cell malignant progression, such as EMT, invasion, and metastasis." (PMID 32242230, 2020). "Bone metastasis tends to occur more frequently in breast cancer that has an increased expression of IL-1B when compared with breast cancer that does not (37% vs. 5%)." (PMID 32674405, 2020). "This could be a possible reason why P2Y2R siRNA itself reduced IL-1β and VEGF-A production below the control level of both cells and even more so in RT-R-breast cancer cells." (PMID 32397236, 2020). "A non-canonical activation of IL-1β-mediated β-catenin signaling is reported to lead to the onset of EMT in breast cancer cells." (PMID 33123472, 2020). "Utilizing the Curtis breast cancer data set, we demonstrated that expression of OSM and IL-1β levels in the breast microenvironment are elevated in breast cancer and that high expression of these cytokines leads to increased metastatic potential and reduced breast cancer patient survival." (PMID 31007849, 2019). "Here, we demonstrate that in the bone metastatic niche, microenvironmental IL1β promotes the ability of breast CSCs to form colonies through activation of NFKB and CREB signalling, Wnt ligand secretion and autocrine Wnt signalling in breast cancer cells." (PMID 31676788, 2019). "By analyzing the data from 719 breast cancer samples in which the luminal is 566, Her2 + is 37, and TNBC is 116, we found that the expression of IL-1β and TNF-α showed a significant increase in TNBC compared with luminal and Her2 + breast cancers (p < 0.005 by the two-sided Student’s t-test)." (PMID 31602400, 2019). "Importantly, these findings also indicate that even when ER+ breast cancer cells, such as T47D cells, are unable to produce IL-6 in response to OSM or IL-1β, they can still undergo invasive characteristics independently of IL-6." (PMID 31007849, 2019). "However, our results for let-7-5p are in agreement with those observed for let7, let-7a, and let-7d that down-regulate IL-6 and IL-10 directly or TNF, IL-6, and IL-1β indirectly in MCF10A, fibroblasts, and breast cancer cells." (PMID 31694049, 2019). "While, IL-1β alone does not appear to affect breast cancer patient survival, high co-expression of OSM and IL-1β also led to decreased patient survival." (PMID 31007849, 2019). "Considering IL-1β and TNF-α effects in the proliferation of breast cancer cell lines, we decided to investigate the relation between the cytokine mRNA levels and survival of breast cancer patients using TCGA data retrieved from the Human Protein Atlas database." (PMID 31093512, 2019). "Furthermore, OSM induces STAT3 phosphorylation and IL-1β promotes p65 phosphorylation to synergistically induce IL-6 secretion in ER− MDA-MB-231 and to a lesser extent in ER+ MCF7 human breast cancer cells." (PMID 31007849, 2019). "Furthermore, these results demonstrate that not only does high expression of each one of these cytokines increase metastasis and decrease survival in breast cancer patients, but OSM and IL-1β also induce the expression of IL-6." (PMID 31007849, 2019). "TGFB1, TNF, IL1B and IL6 are inhibited by ligand-bound AhR in ERα-positive breast cancer cells." (PMID 29320557, 2018). "Furthermore, it was demonstrated that signaling mediated by the G protein estrogen receptor (GPER) cells, induced by estrogen, triggered IL-1β and IL-1R1 expression in CAF and in breast cancer cells." (PMID 30042333, 2018).
breast cancer (continued). "Even though AA also induced NF-κB nuclear translocation, this fatty acid was not able to increase other pyroptosis-related parameters like active caspase-1 and secreted IL-1β, indicating that DHA-induced pyroptosis cell death triggered in breast cancer cells is a specific event." (PMID 29386662, 2018). "In addition, breast cancer cell lines that specifically home to and colonise mouse bone (MDA-IV) have been shown to express high levels of IL-1B." (PMID 29760166, 2018). "There is no direct evidence for NLRP3 inflammasomes in breast cancer; however, indirect evidence implicates a role of inflammasome activation in breast tumour development through IL-1β." (PMID 30447690, 2018). "Inhibition of IL-1B in metastatic breast cancer cells resulted in no chemokine production by MSCs, whereas overexpression of IL-1B in non-metastatic breast cancer cells increased chemokine levels in MSCs." (PMID 29760166, 2018). "Furthermore, cell from normal mammary epithelium and breast cancer cell lines expressed ICAM1 upon stimulation with the proinflammatory cytokines TNFα, IL1β and IFNγ." (PMID 30082828, 2018). "In addition, we measured the concentrations of G-CSF, IL-1β, IL-6, CCL4 and TNFα in the plasma of the mice with breast cancer." (PMID 28178994, 2017). "Consistently, elevated expressions of MCT2 as well as β-hydroxybutyrate-induced genes, IL-1β and LCN2, are significantly (P values: MCT2/IL-1β=0.029; MCT2/LCN2=0.017, log-rank test) correlated with poor prognosis in breast cancer patients in two independent cohorts." (PMID 28281525, 2017). "However, upon treatment with honokiol (Group IV), mammary cancer bearing animals showed significant (p < 0.05) reversal in inflammatory cytokines levels of TNF-α, IL-1β, and IL-6." (PMID 28620301, 2017). "We therefore asked whether breast cancer cells with higher basal OPG and IL1B secretion levels show different responses to IL1B-induced OPG expression." (PMID 28143606, 2017). "Interestingly, the EMT6 tumor microenvironment contained more inflammatory cytokines, including IL-1β and GM-CSF, than EMT6siCD200 tumors, which is consistent with a role for these cytokines in promoting tumor growth in the EMT6 breast cancer model." (PMID 28234914, 2017). "We found that regardless of the basal OPG and IL1B levels, all breast cancer cell lines remained responsive to IL1B-mediated OPG induction, with the highest induction of OPG secretion in the non-TNBC cells." (PMID 28143606, 2017). "We show that OPG secretion is induced by IL1B in a p38- and p42/44-dependent manner, independent of breast cancer subtype or basal OPG levels." (PMID 28143606, 2017). "Therefore our results show that IL1B-induced OPG secretion is regulated by the p38 and p42/44 MAPK pathways in breast cancer cells." (PMID 28143606, 2017). "Most of the breast cancer survivors in this study (>80%) had received a chemotherapeutic cocktail including doxorubicin, which was shown in an animal model to increase TNF-α (and IL-1β) in the hippocampus." (PMID 28616125, 2017). "Furthermore, the expressions of IL-1β and LCN2 were also induced in breast cancer cells co-culture with MGDAs." (PMID 28281525, 2017). "Furthermore, the expressions of IL-1β and LCN2 mRNA were positively correlated with MCT2 expression in breast cancer specimens." (PMID 28281525, 2017). "Furthermore, previous literature reported high circulating levels of IL6 and IL8 in patients with BM, and that patients suffering from pain with advanced breast cancer have high systemic levels of the inflammatory mediators TNF, IL-1b, and IL6." (PMID 28903357, 2017). "Furthermore, we showed relative to normal breast tissue that elevated levels of CCL2, IL1B and OPG mRNA levels were detected in stage I breast cancer human tissue samples." (PMID 28143606, 2017). "In the same case, IL-1β and its receptor IL-1R1 are upregulated in breast cancer cells that metastasize to bone comparing with non-metastasis cells." (PMID 28927416, 2017).
breast cancer (continued). "For instance, IL1β/IL1R1 system has been shown to up-regulate PTGES, which is a key enzyme involved in the production of COX2 and prostaglandin E2 that promote the motility of breast cancer cells." (PMID 27072893, 2016). "In the present study, the underlying mechanism by which IL-6 production is induced in luminal-type breast cancer cells was evaluated, and TG2 overexpression, IL-1β stimulation, and IL-6 expression were found to give cancerous cells a hormone-independent phenotype." (PMID 27609180, 2016). "Among patients with breast cancer who were under treatment of coenzyme Q10 (100 mg/day) and vitamin B group (riboflavin 10 mg and niacin 50 mg), inflammatory markers included TNF-α, IL-8, IL-6, IL-1β were significantly decreased." (PMID 27047809, 2016). "Treatment of luminal-type breast cancer cells with IL-1β did not induce IL-6 production in this study." (PMID 27609180, 2016). "The beneficial role of yoga has also been demonstrated in non-pregnant women, where an RCT study of breast cancer survivors showed a significant dose-response decrease in serum IL-1β and IL-6 in those who practiced yoga." (PMID 27348869, 2016). "In fact, WBC, which is recognized as a strong indicator of inflammation promoting cardiovascular events, was not correlated with ox-LDL, IL-1β and TNF-α, whereas these biomarkers yielded significant associations with breast cancer in the present study." (PMID 27391324, 2016). "Moreover, inflammatory cytokines, such as interleukin (IL)-6, induce LCN2 expression depending on activation of the STAT3 signaling pathway, IL-1β and the tumor cell-derived factor IL-10 also promote LCN2 expression in lung and breast cancer." (PMID 27912767, 2016). "On the basis of these results, it could be assumed that estrogenic GPER signalling couples the expression of both IL1β in CAFs and IL1R1 in breast cancer cells, thus generating a feedforward IL1beta/IL1R1 response." (PMID 27072893, 2016). "Collectively, these findings suggest that estrogenic GPER signalling generates a feedforward loop that couples IL1β induction in CAFs to IL1R1 expression by cancer cells, hence contributing to the functional cross-talk between the tumor microenvironment and breast cancer cells." (PMID 27072893, 2016). "Although pro-inflammatory cytokines such as IL-1β and TNFα induce IL-6 production from innate immune cells during acute inflammation, this is not the case in human breast cancer cells." (PMID 27609180, 2016). "The activities of CAFs and MSCs in breast cancer are integrated within an intimate inflammatory tumor microenvironment (TME) that includes high levels of tumor necrosis factor α (TNF-α) and interleukin 1β (IL-1β)." (PMID 25928089, 2015). "Although cytokines such as TNF-α, TGF-1, IL-6, and IL-1β are capable of inducing EMT in breast cancer cells, the source of these factors has not been studied." (PMID 26207636, 2015). "IL-6, MCP-1, and TNFα are elevated in mouse wound healing models but not in this breast cancer model, except for IL-1β, elevated in both models." (PMID 26113869, 2015). "In addition, GTCpFE was found to inhibit NFκB activity in other breast cancer cell lines, such as BT474 and MDA-MB-231, and in response to other cytokines, including IL-1β." (PMID 26530254, 2015). "Upon activation by various stimuli, including IL-1β, NFκB transcriptionally regulates several genes involved in early inflammatory responses, such as the chemokine CXCL8, in a variety of cells, including breast cancer cells." (PMID 26696754, 2015). "We measured in the supernatant of metastatic and non-metastatic breast cancer cells the production of IL-1β, a known inducer of NF-κB pathway and chemokine expression." (PMID 26362269, 2015). "IL-19 induces IL-1β, IL-6, TGF-β, and MMP-2 in breast cancer cells." (PMID 23710200, 2013). "We found that the high level of IL-1β but not IL1-α was significantly correlated with a poor brain metastasis-free survival of breast cancer patients." (PMID 23495140, 2013).